POSTN (periostin)
Diseases named in the same sentence as POSTN in open-access papers (continued):
Sharing a sentence is not in itself a finding about the gene and the disease.
breast carcinoma (142 papers, 2006 to 2026). "This differs from splice variant expression in chondrocytes and breast cancer, suggesting a cell type-specific expression and function of Periostin." (PMID 39940700, 2025). "Periostin has been reported to be highly expressed in several cancer types, including breast cancer, and it has been associated with osteoblast adhesion and cancer cell migration and is also involved in tumor angiogenesis." (PMID 37629204, 2023). "The enhanced expression of periostin is associated with various pathological conditions including inflammation and disease, and many types of cancer including colon, lung, and breast cancer, and head and neck carcinomas." (PMID 37092398, 2023). "In breast cancer and skin melanoma, stromal periostin expression is significantly associated with the number of infiltrated M2 macrophages, which are essential components of the tumor immune microenvironment involved in tumor progression and metastasis." (PMID 35850759, 2022). "For example, POSTN has high expression in breast cancer, and expression has a positive correlation with the pathological TNM stage; POSTN expression is also associated with lymph node metastasis in breast cancer." (PMID 35057799, 2022). "Nowadays, studies revealed that periostin is associated with multiple cancers such as colon, pancreatic, ovarian, breast cancer." (PMID 35366885, 2022). "In breast cancer patients with high periostin, the risk of bone metastases is enhanced by elevated CTHRC1 expression." (PMID 36190948, 2022). "Previous studies have also confirmed that high serum POSTN levels are associated with the prognosis of several cancers, such as breast cancer, ovarian cancer, colorectal cancer, and pancreatic cancer." (PMID 35508298, 2022). "In this study, we compared the distribution of POSTN variants in breast cancer using antibodies against POSTN exon 17 (C-terminal) and POSTN exon 12 (N-terminal) and investigated the association between POSTN exon 17 and wnt3a." (PMID 33919736, 2021). "In another report, POSTN protein expression was increased in CD44high/CD24low breast cancer stem cells, compared with control cells, and associated with cancer stem cell chemotherapy resistance." (PMID 33919736, 2021). "In breast cancer POSTN was elevated in malignant cells and associated with poorer patient progression free and overall survival." (PMID 31572679, 2019). "In breast cancer patients, survival analysis showed that high expression of POSTN predicted a significantly higher risk of recurrence specifically in basal-like breast cancer, which is largely overlapped with histologically-defined TNBC." (PMID 29507310, 2018). "A number of studies have examined the association between periostin expression and prognostic tumor features in patients with breast cancer, although few studies have assessed the association between periostin expression and breast cancer prognosis." (PMID 29161296, 2017). "More recently, polymorphisms in the POSTN gene have been associated with breast cancer susceptibility." (PMID 27708222, 2016). "The underlying genetic mechanism of periostin regulating the breast cancer CSC is still unclear, however, and needs further investigation." (PMID 23056395, 2012). "In particular, we have previously reported the importance of inhibiting the pathological POSTN splicing variant with exon 21 (PN1-2) in chemotherapy-resistant breast cancer, malignant melanoma, diabetic retinopathy, inflammatory bowel disease, atherosclerosis, aortic aneurysm, etc.." (PMID 39195230, 2024). "In breast cancer patients, elevated plasma periostin levels were associated with bone metastasis." (PMID 38279150, 2024). "Additionally, POSTN has been associated with the augmentation of the Wnt signaling pathway in mouse breast cancer stem cells." (PMID 38375508, 2024).
breast carcinoma (continued). "By reanalyzing these scRNA‐seq datasets, we noticed that SPARC mRNA was expressed by different CAF subsets, especially myofibroblast‐like and inflammatory‐like CAFs, as well as POSTN, a gene encoding periostin, a protein that is secreted by CAFs with pro‐tumor activity in breast cancer." (PMID 36346290, 2023). "Although overexpression of periostin in cancer-associated stroma and/or in cancer cells has been associated with poor clinical outcome in various types of cancer, its influence on the clinical outcome of breast cancer has received little attention." (PMID 29161296, 2017). "Moreover, periostin has been implicated in the metastatic process of many cancers, including for example breast cancer, colon cancer, head and neck cancer, ovarian cancer, and pancreatic ductal adenocarcinoma." (PMID 28977942, 2017). "Our data obtained using both phyllodes tumors and breast cancer cells raise the possibility that knockdown of periostin in cancer cells may cause an effect similar to that of decorin produced by fibroblasts and myofibroblasts." (PMID 25400079, 2014). "The growth of pulmonary metastases spontaneously arising from either autochthonous MMTV-PyMT breast carcinoma cells or orthotopically implanted POSTN-deficient breast carcinoma cells, was also attenuated with the POSTN−/− background as compared to the control POSTN+/+ background." (PMID 24216702, 2013). "These outcomes suggest that periostin is associated with breast cancer CSC, suggesting that its expression may be implicated in self-renewal and tumorigenesis by activating its downstream target genes." (PMID 23056395, 2012). "Interestingly, whereas periostin was associated with good survival in breast cancer patients, its overexpression was associated with poor prognosis in prostate cancer patients." (PMID 21611158, 2011). "One of the most highly overexpressed genes in this category, that encoding periostin, was analysed immunohistochemically on breast cancer tissue microarrays and its expression in neoplastic cells correlated with poor outcome in a cohort of poor prognosis estrogen receptor-positive tumours." (PMID 17014703, 2006). "Furthermore, POSTN is reported to be associated with a poor prognosis for basal-like breast cancer, with POSTN-integrin ɑvβ3 signaling required to establish a micro-environmental niche for breast cancer stem cells." (PMID 36593497, 2023). "Induction of periostin by transforming growth factor β3 facilitates breast cancer metastasis to the lung and survival of cancer cells in this organ, and increased plasma levels of this molecule have been linked to a higher risk of secondary breast cancer foci in the bone." (PMID 35268340, 2022). "Therefore, although the functional differences among POSTN in the stroma and cancer cells in many cancer types remain unclear, it is evident that both variants of POSTN are poor prognostic markers of breast cancer." (PMID 33919736, 2021). "Finally, cathepsin K was demonstrated to cleave periostin, which may be linked to breast cancer bone metastasis." (PMID 30897858, 2019). "POSTN expressed in cancer-associated fibroblasts or other stromal cells may facilitate the aggressiveness of pancreatic cancer, ovarian cancer, prostate cancer, esophageal adenocarcinoma, gastric cancer, breast cancer, and cholangiocarcinoma." (PMID 26556874, 2016). "To date, POSTN expression has been demonstrated in canine tumours such as mammary carcinoma, bladder carcinoma, osteosarcoma and squamous cell carcinoma of the skin, whereas there is no information on its expression in canine testicular tumours." (PMID 41361308, 2025). "In a breast cancer mouse model, anti-periostin antibody inhibited primary tumor growth, metastatic lesions, and increased the survival rate, making periostin a potential target, notably for blocking the partial-EMT state." (PMID 40076457, 2025).
breast carcinoma (continued). "The cardiokine potentially involved, periostin, was increased in the cardiac tissue and serum of a cardiac hypertrophy model, and was reported to increase breast cancer cell proliferation." (PMID 38279150, 2024). "When taken together with their ARPs and active signaling nodes using ligands, such as periostin, the results suggest CAFs as drivers of increased desmoplasia, chemoresistance, and promotion of cancer cell invasion with age in ER+ breast cancer." (PMID 39483921, 2024). "ATF3-transgenic mice with orthotopic breast cancer, which showed enhanced tumor growth, exhibited increased cardiac expression of periostin, CTGF, FN, SerpinA3, and CP." (PMID 38279150, 2024). "In the low-dose PE-induced LV hypertrophy with orthotopic breast cancer model which resulted in increased the tumor growth, increased cardiac expression of periostin and FN was demonstrated." (PMID 38279150, 2024). "In cancer patients, periostin expression was increased in various types of cancer tissues, including colon, prostate, NSCLC and breast cancer, and was associated with poor survival." (PMID 38279150, 2024). "Upregulation of periostin was shown to stimulate lung cancer cell proliferation and migration, promote tumor angiogenesis in breast cancer cells, and promote colon cancer cell survival under stress conditions." (PMID 38279150, 2024). "It was further suggested that POSTN in breast cancer cells promotes activation of adipose‐derived cells to become CAF‐like cells." (PMID 38389400, 2024). "Previously, we reported that PN17-Ab detected pathological POSTN with exon 17 in MDA-MB 231 breast cancer cells by western blotting." (PMID 39272982, 2024). "For example, the upregulation of the ECM molecule periostin has been shown to promote the reawakening of breast cancer cells from dormancy." (PMID 37092398, 2023). "The presence of periostin was validated in a pilot cohort of samples from breast cancer patients with localized disease or lymph node metastasis." (PMID 37893211, 2023). "This localized TGF-β activation increases periostin expression, thereby triggering dormant breast cancer cells to enter a proliferative state." (PMID 37440925, 2023). "It has recently been reported that lung fibroblast-derived POSTN is an important limiting factor of metastatic breast cancer cells within the lung by promoting of the self-renewal of breast cancer stem cells." (PMID 36593497, 2023). "Periostin was reported to bridge the colonization of breast cancer cells to their terminal lung-metastatic site, placing its involvement at the distal end of the metastatic cascade." (PMID 37069149, 2023). "The results revealed that POSTN expression was significantly higher in breast cancer tissues than in normal breast tissues." (PMID 37716956, 2023). "A recent study has reported that serum periostin is a prognostic biomarker for breast cancer-specific survival." (PMID 38041134, 2023). "The acquired expression of POSTN correlated with poor prognosis and survival in breast cancer patients." (PMID 37919719, 2023). "In the subclasses of breast cancer, POSTN expression was highest in the luminal subtype of breast cancer, followed by the HER2–positive and TNBC subtypes, suggesting that periostin plays a critical role in breast cancer." (PMID 37716956, 2023). "In human mammary epithelial cells, POSTN provided breast cancer cells with a stem-cell-like phenotype." (PMID 36902188, 2023). "In terms of treatment, neutralization of POSTN with appropriate antibodies has been shown to reduce breast cancer metastasis to the lung." (PMID 37143134, 2023). "Previous research has also indicated high expression of periostin in breast cancer patients with bone metastasis." (PMID 38041134, 2023). "Periostin, an extracellular matrix component, was described as a metastatic breast cancer biomarker identified in exosomes." (PMID 37629204, 2023).
breast carcinoma (continued). "In breast cancer tumour samples CTHRC1 protein levels are significantly upregulated with POSTN and MMP13, further supporting the need to evaluate their crosstalk in cancers." (PMID 36190948, 2022). "Many reports have suggested that increased POSTN expression significantly enhances angiogenesis in breast cancer." (PMID 36077762, 2022). "In human breast cancers, periostin overexpression also leads to a substantial increase in angiogenesis." (PMID 36224629, 2022). "POSTN inhibition has been reported to overcome chemoresistance via reducing the expansion of mesenchymal tumor subpopulations in breast cancer." (PMID 35268340, 2022). "In a mouse model of MMTV-PyMT, periostin is required for the formation of an immunosuppressive pre-metastatic niche in the lungs during breast cancer metastasis by recruiting MDSCs and activating ERK, AKT, and STAT3." (PMID 36224629, 2022). "In lung metastases of the MMTV-PyMT mouse breast cancer model, CD90+ CSCs were observed to preferentially localize in the proximity of stromal niches and periostin-deficient animals exhibited a reduction in the CSC population." (PMID 36224629, 2022). "An anti-periostin peptide was synthesized and proved to reverse resistance to doxorubicin in breast cancer cells." (PMID 35707463, 2022). "A similar inverse interaction between FGF1 and periostin has been observed in breast cancer where FGF1 repressed periostin expression through a PKC-dependent pathway." (PMID 35883655, 2022). "Proteomics data for breast cancers in revealing CTHRC1 overexpression with POSTN and MMP13 further strengthens the need to look at this gene network in other cancers." (PMID 36190948, 2022). "The proliferation ability of breast cancer cells with POSTN expression was significantly enhanced, and the tumor formation test revealed that the vessel density was significantly increased." (PMID 35832544, 2022). "For example, Tenascin C (TNC) and periostin (POSTN) play important roles in both the survival and maintenance of stem cell functions of disseminated breast cancer cells and are required for metastatic outgrowth." (PMID 35737114, 2022). "In breast cancer lung metastases, stromal POSTN is crucial for cancer stem cell maintenance by increasing Wnt signaling 36, and LTBP2+/POSTN+ CP-CAFs constitute the majority of ECM-CAFs." (PMID 36438498, 2022). "In breast cancer the endothelial tip cells deliver periostin, thus contributing to the development of the perivascular niche." (PMID 35056404, 2022). "A study using a murine breast cancer model found POSTN was necessary for cancer stem cell maintenance and survival in the metastatic niche by increasing Wnt signalling—a core pathway in CRC tumourigenesis." (PMID 34874125, 2022). "It was found that increased periostin expression had a significant correlation with breast cancer progression using quantitative real-time PCR and western blot analysis." (PMID 36224629, 2022). "Periostin is overexpressed in raised mammographic density and in most breast cancers, where it enhances angiogenesis and tumor progression, and recruits Wnt ligands to maintain cancer stem cell maintenance." (PMID 35954468, 2022). "Breast cancer cell lines overexpressing periostin enhance tumor angiogenesis in vivo by activating FAK signaling via integrin-v3 and upregulating the VEGF receptor Flk-1/ KDR in endothelial cells." (PMID 36224629, 2022). "The proangiogenic activity of periostin is reported in gliomas, breast cancer, pancreatis cancer and liver metastases in CRC; however, in primary colorectal cancer, it has been poorly investigated." (PMID 35056404, 2022). "POSTN also has high expression in a variety of malignant tumor-related interstitial cells, including non-small cell lung cancer, breast cancer, ovarian cancer, and thymoma." (PMID 35057799, 2022). "Another study reported that POSTN was located in the cytoplasm and membrane of cancer cells from patients with breast cancer with lymph node metastasis." (PMID 33919736, 2021).
breast carcinoma (continued). "As periostin is highly expressed in breast cancer stem cells and is known to maintain it, SUM159PT TNBC cell lines were intended for further analysis." (PMID 34680221, 2021). "POSTN gene expression is upregulated in most common tumours, including breast cancer, pancreatic cancer, melanoma, and colon cancer, and it plays an important role in the development of tumours, especially in the metastasis of tumours." (PMID 34193219, 2021). "To examine the localization of POSTN according to the epitope of the POSTN antibody, we used primary tissue obtained from patients with breast cancer." (PMID 33919736, 2021). "Our results showed that POSTN was highly expressed in patients with breast cancer or mouse tumor models when immunostaining was performed on the sections that were isolated using the monoclonal Ex17 antibody." (PMID 33919736, 2021). "This is consistent with a previous report that one of the effects of POSTN is to increase the prevalence of breast cancer stem cell phenotypes." (PMID 33513753, 2021). "They showed that how periostin promotes at the early stage of breast cancer, and the pulmonary accumulation of myeloid-derived suppressor cells which in turn indicates the potentiality of periostin for the prevention and treatment of breast tumor metastasis." (PMID 32688410, 2020). "In breast cancer metastasis, endothelial tip cells within the perivascular niche deposit increased levels of periostin, tenascin-C, versican, S100 proteins, TGFβ and MIF, which act to maintain cancer cell dormancy." (PMID 33014869, 2020). "In support of our in vivo findings, we observed that treatment of lung fibroblasts by TN EVs significantly increased periostin and fibronectin expression relative to EVs from luminal A or control breast cancer cells." (PMID 31936750, 2020). "In metastatic breast cancer models, TGFβ2 and TGFβ3 expressed by disseminated tumor cells induce periostin expression in lung fibroblasts and endothelial tip cells." (PMID 33014869, 2020). "In a breast cancer study, the silencing of periostin expression by siRNA in CSCs isolated from tumor patients led to increased sensitivity to CIS, docetaxel, and epirubicin." (PMID 31412536, 2019). "Previous studies have identified stromal fibroblasts as the stem cell niche responsible for the production of periostin, a component of the extracellular matrix, to recruit Wnt1 and Wnt3A and then activate Wnt signaling in breast cancer stem cells." (PMID 30999932, 2019). "These infiltrating breast cancer cells induce lung fibroblasts expressing periostin to maintain stemness to achieve initial metastasis colonization." (PMID 30999932, 2019). "The extracellular matrix protein periostin is also involved in lung metastatic development since periostin knock-out mice develop mammary tumors with a reduced number of lung metastases compared to periostin wild-type animals." (PMID 31330946, 2019). "Thus, serum POSTN levels in patients with cholangiocarcinoma were significantly increased compared with that in healthy controls, patients with benign liver diseases, and even patients with breast cancer, indicating that serum POSTN levels could be used as a diagnostic biomarker." (PMID 29946533, 2018). "These stromal fibroblasts, stimulated with tumor-derived TGF-β, produce periostin in a mouse model of breast cancer." (PMID 30061895, 2018). "In another study, breast cancer stem cells were shown to induce periostin expression in fibroblasts to aid metastatic colonization, presumably because deposition of periostin creates a supportive microenvironment which resembles that of the primary niche." (PMID 29903049, 2018). "In contrast, another report found that periostin is a key factor for metastatic colonization in breast cancer through the maintenance of cancer stem cells." (PMID 30131847, 2018). "For example, mammary cancer cells can induce ECM periostin production by stromal fibroblasts, essential for CSC maintenance by promoting Wnt signaling." (PMID 30356678, 2018).